ACTR3B (actin related protein 3B)
Description:
Plays a role in the organization of the actin cytoskeleton. May function as ATP-binding component of the Arp2/3 complex which is involved in regulation of actin polymerization and together with an activating nucleation-promoting factor (NPF) mediates the formation of branched actin networks. May decrease the metastatic potential of tumors.
Synonyms: ARP11; ARP3beta
Tractability: PROTAC: ubiquitination databases record sites on it; its protein half-life has been measured.
Gene: Protein-coding gene on chromosome 7 (152,759,749 to 152,855,378, forward strand). Ensembl gene ENSG00000133627.
Subcellular location: Cytoplasm, cytoskeleton; Cell projection
Gene Ontology:
Cellular component: extracellular exosome; actin cytoskeleton; cytoskeleton; lamellipodium
Genetic constraint (gnomAD): Loss-of-function variants: 8 observed, 44.01 expected, observed/expected ratio (o/e) 0.18, 90% interval 0.11 to 0.33. The upper end of that interval is the gene's LOEUF score, 0.33, which puts it in group 1 of 6, group 1 being the genes least tolerant of losing a copy. Missense variants: 242 observed, 450.83 expected, observed/expected ratio (o/e) 0.54, 90% interval 0.48 to 0.6. Synonymous variants: 144 observed, 161.62 expected, observed/expected ratio (o/e) 0.89, 90% interval 0.78 to 1.02.
Homologues: Orthologues: chimpanzee ACTR3B (100% identical), macaque ACTR3B (100% identical), mouse Actr3b (99% identical), rat Actr3b (92% identical), dog ACTR3B (92% identical), zebrafish actr3b (90% identical), pig ACTR3B (88% identical). Paralogues in human: ACTR3 (90% identical), ACTR3C (46% identical), ACTA1 (39% identical), ACTA2 (39% identical), ACTC1 (39% identical), ACTG2 (39% identical), ACTB (39% identical), ACTG1 (38% identical), ACTBL2 (36% identical), ACTR1A (35% identical), ACTR1B (34% identical), ACTR2 (32% identical), and 14 more.
Diseases named in the same sentence as ACTR3B in open-access papers:
ACTR3B is named in the same sentence as 7 diseases in open-access papers, as found by Europe PMC text mining. Sharing a sentence is not in itself a finding about the gene and the disease. The quoted sentences say what the papers report.
colorectal cancer (1 paper, 2022). A primary or metastatic malignant neoplasm that affects the colon or rectum. "ACTR3B (actin-related protein 3B) protein expression has been linked to colorectal cancer invasion and proliferation, it is part of a complex with CAPG and CD3D that interacts with several HIV proteins and its expression aids SARS-CoV-2 binding and intracellular processing." (PMID 36299731, 2022).
polycystic kidney (1 paper, 2013). "Case 5 carried CTNNA3 and ACTR3B duplication, and exhibited open spina bifida, kidney agenesis and polycystic kidney phenotype." (PMID 23349908, 2013).
cancer (2 papers, 2017 to 2022). A tumor composed of atypical neoplastic, often pleomorphic cells that invade other tissues. "ALB and SQLE were upregulated in the “amino acid metabolism, increased albumin levels, and molecular transport” network at all time points, and actin-related protein 3B (ACTR3B) was upregulated in the “cancer, hematological disease, and immunological disease” network at all time points." (PMID 36299731, 2022).
tumor (2 papers, 2021 to 2022). "In women, the ACTR3B gene showed concordance and a high frequency of somatic mutation in most tumor/plasma pairs." (PMID 34680380, 2021).
ACTR3B also shares sentences with these, for which no sentence is quoted: hematological disease (1 paper); prostate carcinoma (1); respiratory depression (1).